TENT4B (terminal nucleotidyltransferase 4B)
Description:
Terminal nucleotidyltransferase that catalyzes preferentially the transfer of ATP and GTP on RNA 3' poly(A) tail creating a heterogeneous 3' poly(A) tail leading to mRNAs stabilization by protecting mRNAs from active deadenylation. Also functions as a catalytic subunit of a TRAMP-like complex which has a poly(A) RNA polymerase activity and is involved in a post-transcriptional quality control mechanism. Polyadenylation with short oligo(A) tails is required for the degradative activity of the exosome on several of its nuclear RNA substrates. Doesn't need a cofactor for polyadenylation activity (in vitro). Required for cytoplasmic polyadenylation of mRNAs involved in carbohydrate metabolism, including the glucose transporter SLC2A1/GLUT1. Plays a role in replication-dependent histone mRNA degradation, probably through terminal uridylation of mature histone mRNAs. May play a role in sister chromatid cohesion. Mediates 3' adenylation of the microRNA MIR21 followed by its 3'-to-5' trimming by the exoribonuclease PARN leading to degradation. Mediates 3' adenylation of H/ACA box snoRNAs (small nucleolar RNAs) followed by its 3'-to-5' trimming by the exoribonuclease PARN which enhances snoRNA stability and maturation.
Synonyms: TRF4-2; PAPD5; TUT3
Tractability: Antibody: its Gene Ontology location is reachable by antibodies, with high confidence. PROTAC: UniProt records ubiquitination sites on it; ubiquitination databases record sites on it.
Target class: Enzyme; Transferase
Gene: Protein-coding gene on chromosome 16 (50,152,911 to 50,235,310, forward strand). Ensembl gene ENSG00000121274.
Subcellular location: Nucleus; Nucleus, nucleolus; Cytoplasm
Subcellular location (Human Protein Atlas): Cytosol; Nucleoli; Plasma membrane
Pathways (Reactome):
Metabolism of RNA: Nuclear RNA decay
Gene Ontology:
Molecular function: guanylyltransferase activity; poly(A) RNA polymerase activity; protein binding; RNA binding; telomerase RNA binding; adenylyltransferase activity
Biological process: carbohydrate homeostasis; histone mRNA catabolic process; miRNA catabolic process; mRNA 3'-end processing; negative regulation of nuclear-transcribed mRNA poly(A) tail shortening; negative regulation of telomere maintenance via telomerase; poly(A)-dependent snoRNA 3'-end processing; polyadenylation-dependent ncRNA catabolic process; positive regulation of 3'-UTR-mediated mRNA stabilization; RNA 3'-end processing; RNA catabolic process
Cellular component: cytoplasm; cytosol; nucleolus; nucleus; TRAMP complex
Genetic constraint (gnomAD): Loss-of-function variants: 8 observed, 64.93 expected, observed/expected ratio (o/e) 0.12, 90% interval 0.071 to 0.22. The upper end of that interval is the gene's LOEUF score, 0.22, which puts it in group 1 of 6, group 1 being the genes least tolerant of losing a copy. Missense variants: 544 observed, 801.14 expected, observed/expected ratio (o/e) 0.68, 90% interval 0.63 to 0.73. Synonymous variants: 332 observed, 327.1 expected, observed/expected ratio (o/e) 1.01, 90% interval 0.93 to 1.11.
Homologues: Orthologues: macaque TENT4B (95% identical), pig TENT4B (94% identical), chimpanzee TENT4B (92% identical), rat Tent4b (90% identical), guinea pig TENT4B (88% identical), mouse Tent4b (87% identical), dog TENT4B (82% identical), tropical clawed frog tent4b (68% identical), rabbit TENT4B (58% identical), zebrafish tent4b (57% identical), Drosophila melanogaster Trf4-1 (38% identical), Caenorhabditis elegans gld-4 (24% identical), and 1 more. Paralogues in human: TENT4A (47% identical).
Diseases named in the same sentence as TENT4B in open-access papers:
TENT4B is named in the same sentence as 14 diseases in open-access papers, as found by Europe PMC text mining. Sharing a sentence is not in itself a finding about the gene and the disease. The quoted sentences say what the papers report.
allergic asthma (1 paper, 2025). A asthma with a basis in a pathological type I hypersensitivity reaction. "Other identified genes, such as TARDBP, TENT4B, and HNRNPL, have not been previously implicated in allergic asthma." (PMID 40504147, 2025).
Obesity (1 paper, 2025). Accumulation of substantial excess body fat. "We found that MORC3, NUP62, CGAS, ABI3, and RPA2 were highly expressed in lean individuals, where as LMNA, ID2, CDKN1A, TENT4B, MME, and MYC were upregulated in the PBMCs of individuals with obesity." (PMID 40847086, 2025). "Transcriptomic analysis further revealed that individuals with obesity had higher expression of cellular senescence-related genes such as ID2, LMNA, and TENT4B in PBMCs compared to lean individuals, with expression levels of these genes significantly decreasing after bariatric surgery." (PMID 40847086, 2025).
cancer (5 papers, 2014 to 2022). A tumor composed of atypical neoplastic, often pleomorphic cells that invade other tissues. "Moreover, human epidermal growth factor receptor 2 (HER2) signaling activates the transcription of mir-21, which is further stabilized by miR-4728-3p through the inhibition of TUT3/PAPD5/TENT4B, suggesting the significance of the non-canonical poly(A) polymerase TUT3/PAPD5/TENT4B pathway in cancer." (PMID 35740302, 2022).
tumor (4 papers, 2014 to 2023). "Interestingly, in HER2-amplified tumours miR-21-5p trimming is controlled by miR-4728-3p-mediated downregulation of TENT4B, leading to high steady-state levels of active miR-21-5p." (PMID 30397099, 2018). "This may be another piece of evidence of TENT4B acting as a tumour suppressor in human cells." (PMID 30397099, 2018).
TENT4B also shares sentences with these, for which no sentence is quoted: breast carcinoma (2 papers); dyskeratosis congenita (1); endometrial cancer (1); heart disease (1); Huntington disease (1); infection (1); neutropenia (1); Thyroid Carcinoma (1); uterine corpus endometrial carcinoma (1); viral infections (1).